CLEC7A (C-type lectin domain containing 7A)
Diseases named in the same sentence as CLEC7A in open-access papers (continued):
Sharing a sentence is not in itself a finding about the gene and the disease.
tauopathy (4 papers, 2021 to 2026). Neurodegenerative disorders involving deposition of abnormal tau protein isoforms (tau proteins) in neurons and glial cells in the brain. "In this study, we reveal that the pharmacological inhibition of Clec7a effectively mitigates tauopathy-associated synaptic degeneration and neuroinflammatory responses in the PS19 tauopathy mouse model." (PMID 40243488, 2025). "In conclusion, our study elucidates the role of Clec7a in microglial synaptic phagocytosis in tau pathology, offering compelling evidence that targeting Clec7a could mitigate synaptic loss and neuroinflammation in tauopathies." (PMID 40243488, 2025). "Cst7, a lysosomal protease inhibitor, has been shown to modulate microglial inflammatory responses in tauopathy models, while Clec7a (Dectin‐1) mediates amyloid‐beta phagocytosis." (PMID 41508419, 2026). "Our analysis revealed a progressive activation of the Clec7a–SYK signaling axis in the hippocampus of PS19 tauopathy mice, correlating with disease progression." (PMID 40243488, 2025). "Mechanistically, we identified MD2 as a synaptic “eat-me” signal on tauopathy-related synapses, recruiting Clec7a+ microglia to drive aberrant synaptic elimination in PS19 mice." (PMID 40243488, 2025). "To explore the role of Clec7a in the PS19 mouse model of tauopathy, we assessed the expression of Clec7a and phosphorylated SYK (p-SYK) in the ventral hippocampus (vHPC), dorsal hippocampus (dHPC), and cortex of PS19 mice and their wild-type (WT) littermates at 3, 6, 9, and 12 months." (PMID 40243488, 2025). "Consistent with findings in 5×FAD mice, our study indicates that Clec7a is significantly upregulated in the vHPC microglia of PS19 mice, a tauopathy model." (PMID 40243488, 2025). "To evaluate the cognitive consequences of Clec7a inhibition, we conducted comprehensive behavioral assessments in PS19 tauopathy mice." (PMID 40243488, 2025). "Unlike previous studies that primarily focused on Clec7a’s role in amyloid pathology, our work provides a more comprehensive analysis of its involvement in tauopathy." (PMID 40243488, 2025).
disseminated candidiasis (3 papers, 2022 to 2023). Systemic candidiasis occurs when Candida yeast enters the bloodstream and may spread (becoming disseminated candidiasis) to other organs, including the central nervous system, kidneys, liver, bones, muscles, joints, spleen, or eyes. "For instance, an SNP in CLEC7A (encoding Dectin‐1), was shown to predispose carriers to chronic mucocutaneous colonization by C. albicans but not disseminated candidiasis." (PMID 36114607, 2023).
experimental autoimmune encephalomyelitis (3 papers, 2022 to 2024). An autoimmune demyelinating disease of the central nervous system that is produced experimentally in animals by the injection of homogenized brain or spinal cord in Freund's adjuvant. "CLEC7a is also upregulated by microglia in mouse models of experimental autoimmune encephalomyelitis, with Clec7a–/– mice displaying more severe disease, although these effects were more likely mediated by CNS-infiltrating myeloid cells than microglia." (PMID 38425429, 2024).
primary immunodeficiency (3 papers, 2021 to 2022). "Therefore, these deleterious CLEC7A variants in themselves do not represent a primary immunodeficiency per se." (PMID 36377664, 2022).
psoriasis (3 papers, 2011 to 2023). An autoimmune condition characterized by red, well-delineated plaques with silvery scales that are usually on the extensor surfaces and scalp. "Another robust feature of human psoriasis was increased expression of C-type lectin domain family 7 member A (CLEC7A/DECTIN-1), which encodes a membrane receptor that mediates Th1/Th17 immune responses." (PMID 21483750, 2011). "In human psoriasis, expression of CLEC7A was elevated 8.7-fold (FDR-adjusted P<1.59×10−58), but expression of the mouse ortholog Clec7a was not altered in the K5-Tie2 phenotype (P = 0.843) and was decreased by 43% in the IMQ phenotype (P = 0.046)." (PMID 21483750, 2011).
staphylococcus aureus infection (3 papers, 2013 to 2024). An infectious process in which the bacteria Staphylococcus aureus is present. "The CLEC7A-related signaling pathways identified are Osteoclast differentiation, Neutrophil extracellular trap formation, Staphylococcus aureus infection, B cell receptor signaling pathway." (PMID 38846954, 2024).
tuberculosis (3 papers, 2017 to 2024). A chronic, recurrent infection caused by the bacterium Mycobacterium tuberculosis. "The DEPRGs were particularly associated with Salmonella infection, Yersinia infection, tuberculosis, CLEC7A/inflammasome pathway, viral protein interaction with cytokine and cytokine receptor, transfer of LPS from LBP carrier to CD14, and neutrophil degranulation." (PMID 35991562, 2022).
type 2 diabetes (3 papers, 2021 to 2024). "Consistent with a proinflammatory state, several key cell surface antigens (Cd4, Cd68, Cd84), immune sensors (Cx3cr1, Clec7a), and macrophage genes (Axl, Slc11a1) were upregulated in hIAPP islets and in type 2 diabetes." (PMID 34554282, 2022).
colorectal tumor (2 papers, 2023 to 2024). "To investigate the potential role of Dectin-1 in intestinal tumorigenesis, we first examined the influence of Clec7a gene deficiency (Clec7a−/−) on the development of colorectal tumor in DSS-treated ApcMin (ApcMin-DSS) mice, in which intestinal adenoma is induced due to enhanced β-catenin activity." (PMID 36932082, 2023). "In the present study, we showed that galectin-9 expression levels in colonic polyps and non-polyp tissues were similar between WT and Clec7a−/− mice, suggesting that β-glucans in food rather than the endogenous ligand is involved in the Dectin-1-dependent regulation of colorectal tumor development." (PMID 36932082, 2023).
dermatophytosis (2 papers, 2017 to 2021). A common fungal infection of the stratum corneum of the skin, hair, or nails by a dermatophyte. "Other studies of a candidate gene for predisposition in patients suffering from superficial dermatophytosis indicated CLEC7A-Y238X, i.e., an early stop codon variant that influences the recognition of fungal β-glucan by the receptor dectin-1." (PMID 33523393, 2021).
glioblastoma (2 papers, 2020 to 2024). The most malignant astrocytic tumor (WHO grade IV). "Considering that mesenchymal glioblastomas are recognized for their particular aggressiveness, these findings substantiate our previous identification of the association of CLEC7A with high malignancy in brain tumors." (PMID 38846954, 2024). "In addition to changes in Mmps, we also found that glioblastoma was associated with an increased expression of mRNAs encoding microglial phagocytic receptors—Cd93, Msr1, Cd36, Olr1, Megf10, Clec7a, and Scarf1." (PMID 32299465, 2020).
intracerebral hemorrhage (2 papers, 2022 to 2024). A cerebrovascular disorder characterized by bleeding into one or both cerebral hemispheres including the basal ganglia and the cerebral cortex. "Fu and colleagues indicated that the inhibition of Clec7a could ameliorate neuroinflammation after intracerebral hemorrhage in mice; Deerhake and others also reported that Clec7a could limit autoimmune neuroinflammation in mice." (PMID 36503542, 2022).
multiple sclerosis (2 papers, 2022 to 2025). A progressive autoimmune disorder affecting the central nervous system resulting in demyelination. "These include, for example, marker genes for disease-associated microglia (DAM), the microglia neurodegenerative phenotype (MGnD), and microglia inflamed in multiple sclerosis (e.g., APOE, CLEC7A, TREM2, CD68)." (PMID 40700130, 2025).
polyp (2 papers, 2020 to 2023). A usually exophytic mass attached to the underlying tissue by a broad base or a thin stalk. "Body weight loss in ApcMin/+Clec7a−/− mice after DSS-treatment was significantly milder than that in ApcMin/+ mice, and at day 28 after DSS-treatment, polyp number in the colon was significantly reduced in ApcMin/+Clec7a−/− mice." (PMID 36932082, 2023). "Decreased Ptgs2 expression in intestinal polyps was also observed in ApcMin/+Clec7a−/− mice, and its expression was only detectable in CD45+ leukocytes, but not in EpCAM+ epithelial cells, in both polyps and non-polyp tissues." (PMID 36932082, 2023).
renal fibrosis (2 papers, 2023 to 2025). A final common manifestation of a wide variety of chronic kidney diseases characterized by glomerulosclerosis and tubulointerstitial fibrosis. "By using public RNA-seq datasets of CKD patients from the Gene Expression Omnibus (GEO: GSE137570), we found that CLEC7A expression was significantly elevated in CKD patients with more severe renal fibrosis and significantly associated with severe renal fibrosis and the decline in eGFR." (PMID 40959267, 2025). "Histology (H&E) detected a progressive renal fibrosis developed in all mouse models in wild-type (WT) mice induced by UUO, FA, and IR, which was associated with a marked upregulation of Clec7a as determined by real-time PCR at the mRNA level and by flow cytometry at the cellular levels." (PMID 40959267, 2025).
ZIKV infection (2 papers, 2022 to 2024). "We found that the expression of a panel of genes known to be specifically induced by microglial activation, including Clec7a, Aif1, Gfap, and Trem2, was significantly increased upon ZIKV infection." (PMID 39273400, 2024). "Axl and Clec7a were significantly up-regulated in response to ZIKV infection in the brain of CC071 as compared to CC001 mice while P2ry12 was significantly down-regulated." (PMID 36539803, 2022).
alcoholic hepatitis (1 paper, 2022). Acute hepatitis resulting from ingestion of alcohol. "Candidalysin, an exotoxin secreted by C. albicans, has also been shown to increase in patients with alcoholic hepatitis and to exacerbate ethanol-induced liver disease by CLEC7A signaling on bone marrow-derived cells in mice." (PMID 35369462, 2022).
Anxiety (1 paper, 2024). Intense feelings of nervousness, tension, or panic often arise in response to interpersonal stresses. "In males born by vaginal delivery, the expression of Cd36 at PND64 was correlated to anxiety at PND55, whilst a correlation between the expression of Clec7a and the number of head dippings in the elevated plus maze was also noted in males born by CSD." (PMID 39616177, 2024).
autism (1 paper, 2015). Persistent deficits in social interaction and communication and interaction as well as a markedly restricted repertoire of activity and interest as well as repetitive patterns of behavior. "CLEC7A alleles and genotypes distribution in patients with classical autism, Asperger and PDD-NOS." (PMID 26352598, 2015).
autoimmune hemolytic anemia (1 paper, 2018). Autoimmune hemolytic anemia (AIHA) is an autoimmune disorder in which various types of auto-antibodies are directed against red blood cells causing their survival to be shortened and resulting in hemolytic anemia. "In addition to the anti-inflammatory potential of sialylated murine IgG1, only galactosylation of murine IgG1 has also induced inhibitory signals in a mouse model of autoimmune hemolytic anemia and via crosslinking the C-type lectin receptor Dectin-1 (Clec7a) with the inhibitory receptor FcγRIIb." (PMID 29867943, 2018).
calcification (1 paper, 2023). Process by which organic tissue becomes hardened by the physiologic deposit of calcium salts. "Similarly, microglia enveloping calcium nodules in the animal model of primary familial brain calcification displayed characteristics of activated microglia, showing upregulation of genes, such as Cd68 and Clec7a, and enrichment of inflammatory pathway genes." (PMID 38188667, 2023).
cervical cancer (1 paper, 2025). A primary or metastatic malignant neoplasm involving the cervix. "Correlation analysis revealed that HSF1 is lowly expressed in cervical cancer, and ROS can promote the expression of HSF1, which in turn promotes the expression of PU.1 (SPI1), and PU.1 (SPI1) promotes the expression of Dectin1 (CLEC7A)." (PMID 40399470, 2025).
colorectal polyps (1 paper, 2023). "Consistent with the observations in Clec7a–/– mice, significantly fewer colorectal polyps developed in laminarin-containing-food-fed mice compared to normal-food-fed mice." (PMID 36932082, 2023). "Thirty-six weeks after AOM administration, we observed that colorectal polyps were developed only in WT but not in Clec7a−/− GF mice, although the colon length of these mice was similar." (PMID 36932082, 2023).
Intellectual disability (1 paper, 2015). "As disease specifiers are expected to be associated with functional grade, at least in terms of degree of the accompanying intellectual disability, we analyzed the distribution of the CLEC7A genotype frequencies according to the IQ score distribution pattern." (PMID 26352598, 2015).
intestinal tumors (1 paper, 2023). "Although we have only compared tumor development between Il22ra2–/– and Il22ra2+/+ mice on the Clec7a–/– background, these results suggest that enhanced expression of Il22ra2 in Clec7a–/– mice protects these mice from intestinal tumor development." (PMID 36932082, 2023). "We further showed that both CD11c–CD11b+Ly6Cint and CD11c–CD11b+Ly6Chi population were reduced in the polyps of ApcMin/+Clec7a−/− mice, suggesting that Dectin-1 signaling facilitates MDSC expansion in intestinal tumors." (PMID 36932082, 2023).
myocardial infarction (1 paper, 2025). Gross necrosis of the myocardium, as a result of interruption of the blood supply to the area, as in coronary thrombosis. "In a mouse model of myocardial infarction, small interfering RNA silencing of Clec7a downregulates the expression of NLRP3, IL-1β, and IL-18, thereby attenuating myocardial injury." (PMID 40243488, 2025).
prion disease (1 paper, 2023). A transmissible disease that is caused by a protein that is able to induce abnormal folding of normal cellular proteins, leading to characteristic spongiform brain changes, which are associated with neuronal loss without an inflammatory response. "Though increased overall during prion disease, the genes Clec7a, Itgam, and Mcoln3 were significantly decreased in CD11c-/- relative to C57BL/6 mice at the clinical stage of prion disease." (PMID 37910561, 2023).
renal cell carcinoma (1 paper, 2020). "High CLEC7A expression has been identified as an adverse prognostic factor in renal cell carcinoma." (PMID 32429253, 2020).
infection (163 papers, 2008 to 2026). The state of being infected such as from the introduction of a foreign agent such as serum, vaccine, antigenic substance or organism. "Consistent with our earlier results, Dectin-1−/− mice (clec7A−/−) on a 129/Sv background showed significantly enhanced susceptibility to infection with C. albicans SC5314." (PMID 23637604, 2013). "In the aggregate, these studies suggest that variants in the CLEC7A/PLCG2/DUOX1/DUOXA1 pathway are not risk factors for primary infection but rather for control of infection (CLEC7A) and dissemination (PLCG2/DUOX1/DUOXA1)." (PMID 37233265, 2023). "Another study using a murine infection model also shows that LC-derived IL-6 is required for the induction of Th17 cells via CLEC7A (C-type lectin receptor for fungal recognition; Dectin-1) on LCs, whereas Th1 differentiation takes place in the absence of CLEC7A1 ligation." (PMID 37629154, 2023). "By contrast, these population CLEC7A variants are relatively benign unless the carrier is traumatically exposed to C. cassiicola or certain other phaeohyphomycetes to instigate disease, after which impaired Dectin-1–dependent immune responses appear to contribute to suboptimal infection control." (PMID 36377664, 2022). "Taken together, these data suggest variants in the CLEC7A/PLCG2/DUOX1/DUOXA1 pathway are not risk factors for primary infection but rather for control of infection (CLEC7A) and dissemination (PLCG2/DUOX1/DUOXA1)." (PMID 36166305, 2022). "Infection with a higher dose of H. capsulatum (5 × 106), Itgam-/-Clec7a-/- mice had significantly greater fungal burden, higher mortality and succumbed at an earlier time point (10 to14 days) compared to Itgam-/-, Clec7a-/- or WT mice." (PMID 26132276, 2015). "It is interesting to note that macrophages in the spleens of Itgam-/-Clec7a-/- mice were greatly diminished (almost exhausted) after infection with a lethal dose of H. capsulatum, presenting a picture that the macrophages are losing the battle to the fungal pathogen." (PMID 26132276, 2015). "Moreover, many receptors and adaptors are downregulated after infection with WT parasites only: Dectin-1 (Clec7a), IL-1 receptor type I, Nlrc4 and Trem1." (PMID 24736445, 2014). "Consistent with the results from microarray experiments, PR/8 infection significantly decreased the mRNA levels of CLEC7A (Dectin 1), macrophage scavenger receptor 1 (MSR1), CD36, and the mannose receptor C type 1 (MRC1) but did not change the expression of MRC2." (PMID 22396727, 2012). "Therefore, the results indicate that the CLEC7A and PROM1 genes are causal genes affected by rs11053595 and rs62290169 SNPs, respectively, whose allelic variations result in disturbances of the cytokine production influencing the innate immune response towards infection caused by P. brasiliensis." (PMID 37108883, 2023). "We detected a 2-fold increase in Clec12a (p < 0.01), but a significant decrease in Clec7a (p < 0.001), Clec4b1 (p < 0.0001), and Clec9a (p < 0.001) at D9, further suggesting that Mincle was the preeminent CLR expressed in the lungs during infection." (PMID 34320039, 2021). "We uncovered that the ego pathway for the Module 2 was CLEC7A/inflammasome pathway, which enables the host immune system to mount a protective T-helper 17 cells (TH17) response against infection." (PMID 28225867, 2017). "It is noteworthy that within our cohort, 26 patients with additional infections carried damaging variants in CLEC7A, PLCG2, or DUOX1/DUOXA1, compared with 6 of 27 patients without additional serious infections (n = 26 of 40 vs. 6 of 27; P = 0.001)." (PMID 36166305, 2022). "Another lone report showed Dectin-1 (Clec7a)-KO mice did not have changed mortality after infection with Mtb, and in fact had slightly lower bacterial burdens compared to WT at 2 and 4 months post infection." (PMID 34276708, 2021).